STAT3 (signal transducer and activator of transcription 3)
Diseases named in the same sentence as STAT3 in open-access papers (continued):
Sharing a sentence is not in itself a finding about the gene and the disease.
enterocolitis (7 papers, 2010 to 2023). An inflammatory process affecting the small intestine and colon. "Mice in which STAT3 is conditionally inactivated in either myeloid cells or enterocytes develop enterocolitis following injections of 250 μg of dsRNA polyInosine-polyCytosine (pIpC) through triggering endogenous production of type I interferon." (PMID 37296943, 2023). "Stat3 deletion in macrophages and neutrophils reportedly promotes enterocolitis development." (PMID 28887478, 2017). "Removal of STAT3-mediated suppression in myeloid cells leads to enterocolitis." (PMID 23950992, 2013). "However, we did not detect apparent enterocolitis in our Stat3 cKO mice, nor have elevated IgE levels or enterocolitis been reported in patients administered anti-Stat3 reagents." (PMID 28887478, 2017). "Moreover, enterocolitis or the presence of F4/80-positive macrophage infiltrate in the colon was not evident in Stat3 cKO mice at this time point." (PMID 28887478, 2017).
food allergies (7 papers, 2019 to 2025). "Compared to other PIDs (even those with significantly elevated IgE levels, such as DN mutations in STAT3), DOCK8 deficiency leads to an extremely high frequency of severe food allergies which is a distinctive aspect of DOCK8 deficiency." (PMID 40040707, 2025). "Ovalbumin (OVA)-induced food allergy can increase the phosphorylation of STAT3 and activate SOCS3." (PMID 40005151, 2025). "Food allergies and anaphylaxis are reported to be markedly diminished in AD-HIES patients with STAT3 mutations compared with other hyper-IgE patients with no STAT3 mutations." (PMID 31730616, 2019).
graft versus host disease (7 papers, 2013 to 2025). An immune system disorder that occurs after allogeneic hematopoietic stem cell transplant and is a reaction of donor immune cells against host tissues. "A previous international study reported a survival rate of 61% among 18 patients with STAT3 GOF mutations following HSCT, with infectious complications and graft-versus-host disease being the primary causes of mortality." (PMID 40703313, 2025). "In scleroderma graft-versus-host disease (GVHD) models, NIC was reported to reverse the clinical symptoms of GVHD, including alopecia, vasculitis, and diarrhea, of which beneficial effects were associated with the inhibition of the STAT3, Wnt/β-catenin, ERK1/2, AKT, and Notch signaling pathways." (PMID 36555754, 2022). "For instance, in graft-versus-host disease, SOCS1 regulates the inflammatory response by suppressing T-cell activation via inhibition of the CSF3R/JAK2/STAT3 signaling pathway." (PMID 40918404, 2025). "As with many other IEIs, allogeneic hematopoietic cell transplantation (HCT) was initially performed as a curative treatment for patients with STAT3-GOF; however, transplantation complications such as infections and graft-versus-host disease often led to patient death or critical adverse events." (PMID 38549698, 2023). "Mechanistically, IL-22 activates signal transducer and activator of transcription 3 (STAT3) signaling to increase antiapoptotic proliferative response in Lgr5+ stem cells, promoting epithelial regeneration and reducing intestinal pathology and mortality from graft-versus-host disease." (PMID 31816903, 2019).
hepatocellular adenoma (7 papers, 2014 to 2025). A benign epithelial neoplasm arising from the hepatocytes. "Studies have also revealed that SHP2-deficient mice present increased STAT3 activity and increased hepatocellular adenomas." (PMID 37298405, 2023). "Recently, mutations of STAT3 have been described that lead to the development of human inflammatory hepatocellular adenomas or large granular lymphotic leukemia." (PMID 24742922, 2014). "Similarly, hyperphosphorylation was also observed for the homologous somatic L78R mutation in STAT3 found in inflammatory hepatocellular adenoma." (PMID 25526807, 2014). "Notably, all six of these tumors were inflammatory hepatocellular adenomas, suggesting the specificity of somatic STAT3 mutations for this type of hepatocellular tumor." (PMID 24995504, 2014). "The association of MAS and hepatocellular adenoma could potentially be explained by STAT3 The association of MAS and hepatocellular adenoma could potentially be explained by STAT3 (inflammatory pathway) activation induced by GNAS activation activation induced by GNAS activation." (PMID 40078582, 2025).
hypothyroidism (7 papers, 2021 to 2024). Abnormally low levels of thyroid hormone. "Whereas, the expression of p-STAT3 only increased in C57BL/6J hippocampus in response to hypothyroidism (strain x treatment interaction p = 0.006)." (PMID 36233235, 2022). "In our view, it is unlikely that this decrease in STAT3 phosphorylation is causally involved in infarct size reduction by hypothyroidism or the lack of canonical TRα signaling." (PMID 36362133, 2022). "In the present study, we reported a new case with STAT3 GOF phenotype suffering from infantile‐onset autoimmune diabetes and hypothyroidism at 7 months, chronic diarrhea from 1 year of age, and postnatal short stature." (PMID 38404237, 2024). "Under hypothyroidism, infarcts were smaller and phosphorylation of ERK, and STAT3 in mouse hearts was decreased." (PMID 36362133, 2022).
ischemia reperfusion injury (7 papers, 2008 to 2022). Adverse functional, metabolic, or structural changes in ischemic tissues resulting from the restoration of blood flow to the tissue (reperfusion), including swelling; hemorrhage; necrosis; and damage from free radicals. "Nevertheless, one in vivo study found that STAT3 activation protects the myocardium from ischemia-reperfusion injury through MT." (PMID 23374901, 2013). "In vitro and in vivo findings of others have provided evidence that Stat3 protects against cardiomyocyte apoptosis in some cardiac insults including ischemia-reperfusion injuries." (PMID 18270592, 2008). "The JAK2/STAT3 signaling pathway is involved in the expression of a large number of cytokines, growth factors, and hormones and also plays a crucial role in protecting the myocardium from an ischemia-reperfusion injury." (PMID 35281544, 2022).
liver cirrhosis (7 papers, 2010 to 2024). "Another study reported that in liver cirrhosis, STAT3 DNA-binding is impaired by raising the expression of Pias3." (PMID 36297027, 2022). "STAT3 activation is an essential signal for liver renewal in cirrhotic livers from the hepatitis C virus (HCV) infection and alcoholics, and suppressing liver renewal in liver cirrhosis might be due to reduced STAT3 activation." (PMID 36297027, 2022). "Based on the PPI network analysis, STAT3 was recognized as a key target that could be harnessed for therapeutic purposes against liver cirrhosis." (PMID 36297027, 2022). "Impaired STAT3 activation and restoration may thus contribute to the development of cell damage, which leads to liver cirrhosis." (PMID 36297027, 2022). "Moreover, others have reported that STX-0119, an inhibitor of STAT3 dimerization, could suppress the progress of liver cirrhosis by obstructing hepatic stellate cell activation." (PMID 36297027, 2022). "L-HDAg can also induce oxidative stress and activate NF-κB and signal transducer and activator of transcription-3 (STAT-3), leading to liver cirrhosis and cancer." (PMID 35634301, 2022). "C/EBPα overexpression inhibits hepatocyte proliferation by downregulating the expression of c-Myc and Cyclin D, reducing signal transducer and activator of transcription 3 (STAT3) phosphorylation, and improving liver function in a clinically relevant liver cirrhosis model." (PMID 36299447, 2022).
lymphoproliferative disorders (7 papers, 2016 to 2025). "Other somatic STAT5B and STAT3 mutations have been identified in lymphoproliferative disorders." (PMID 30573779, 2019). "Constitutive JAK/STAT3 signaling contributes to disease progression in many lymphoproliferative disorders." (PMID 29228628, 2017). "Our findings show alternative approaches to inhibit STAT3 activity and suggest Hsp90 as a therapeutic target in lymphoproliferative disorders with constitutively active STAT3." (PMID 29228628, 2017). "We hypothesized that both HDAC and JAK/STAT pathways were important in lymphoproliferative disorders, and that inhibiting JAK/STAT3 and HDAC simultaneously might enhance the efficacy of momelotinib and citarinostat without increasing toxicity." (PMID 32394008, 2020). "However, in lymphoproliferative disorders, JAK kinases activated by genetic alterations or cytokine stimulation are presumably responsible for mutant STAT3 hyperactivation." (PMID 29228628, 2017).
mental disorder (7 papers, 2017 to 2024). A disease that has its basis in the disruption of mental process. "Several indications for an interrelationship between STAT3 and the serotonergic neurotransmission system, highly implicated in the aetiology of psychiatric disorders, have also recently emerged." (PMID 33046834, 2021). "Here we used a combinatorial approach to examine the involvement of a specific molecular element, Signal transducer and activator of transcription 3 (STAT3), for behavioural phenotypes with relevance across traditional psychiatric disease entities and to interrogate the underlying neural principles." (PMID 33046834, 2021). "Since substance use disorder is highly comorbid with other forms of mental illnesses relevant to the observed behaviours, this association appeared particularly poignant and we hypothesised that STAT3 KO mice may by extension show altered behaviour relating to amphetamine addiction." (PMID 33046834, 2021). "IL-6/STAT3 pathway has been reported to be involved in chronic pain and mental disorder, so we tested the role of IL-6/STAT3 pathway in the SNI-induced comorbid-like behavior in rats." (PMID 35690777, 2022). "Due to this converging evidence, we hypothesised an important role for STAT3 signalling, specifically within the serotonergic system of the brain, in the regulation of behavioural traits relevant to mental illness." (PMID 33046834, 2021).
neurofibroma (7 papers, 2015 to 2025). An intraneural or extraneural neoplasm arising from nerve tissues and neural sheaths. "The genetically engineered mouse model will be utilised to test whether blockade of STAT3 in earlier stages of NF1-associated nerve sheath tumour progression in plexiform neurofibroma and/or MPNST may have utility in MPNST chemoprevention." (PMID 33658640, 2021). "We found that malignant transformation of plexiform neurofibroma and ANNUBP precursor tumours to MPNST was associated with significant upregulation of p-STAT3 and Ref-1 in these genetically engineered mice." (PMID 33658640, 2021). "Malignant transformation of plexiform neurofibroma and ANNUBP precursor tumours to MPNST was associated with marked upregulation of p-STAT3 and Ref-1 in these genetically engineered mice." (PMID 33658640, 2021). "MEK (MAPK kinase) inhibitors and cucurbitacin-I, an inhibitor of signal transducer and activator of transcription-3 (STAT3) signaling, have shown promise in decreasing the size of neurofibromas and of MPNSTs." (PMID 26203125, 2015). "In addition, small-molecule-mediated inhibition of STAT3 signaling downregulated Ccl2/Ccl12 chemokines, which impaired neurofibroma macrophage populations." (PMID 36982554, 2023). "The observed increase in this GEMM model confirmed a study comparing human MPNST to neurofibromas in which p-STAT3 also appeared to play a role in the progression of the disease, but was in contrast to our data in human samples where the p-STAT3 levels remained constant." (PMID 33658640, 2021). "We examined the expression of p-STAT3 and Ref-1 in mice that have conditional ablation Nf1 and Arf in neural crest-derived Schwann cells that spontaneously develop a full spectrum of NF1-associated nerve sheath tumours including plexiform and atypical neurofibroma as well as MPNST." (PMID 33658640, 2021). "Nf1-Arfflox/flox;PostnCre mice exhibited high expression of Ref-1 and p-STAT3 in MPNST as compared to plexiform and atypical neurofibroma precursor tumours." (PMID 33658640, 2021). "Following these investigations, the role of STAT3 in NF1 tumor development and progression was further explored, with STAT3 shown to contribute to neurofibroma initiation and growth by promoting macrophage recruitment and cytokine production within the tumor microenvironment." (PMID 41294711, 2025).
periodontal disease (7 papers, 2013 to 2025). "This miRNA also attenuates the polarization of macrophage to M2 phenotype by targeting STAT3.64 miR-147 and miR-24 are also other miRNAs which are associated with macrophages and periodontal disease." (PMID 37646047, 2022). "Further, miR-125a may cause reduction of IFN-γ, IL-13, and STAT3 by directly targeting them. miR-29 family which consists of miR-29c, miR-29a, and 29b is very important in the pathogenesis of periodontal disease." (PMID 37646047, 2022). "CXCL10 and ICAM-1 expression were both suppressed when inhibitors of NF-κB and STAT3 were introduced, indicating that OSM-mediates STAT3 signaling and IL-1β-mediated NF-κB signaling may promote infiltration and retention of Th1 cells, leading to periodontal disease." (PMID 37841259, 2023).
Pruritus (7 papers, 2021 to 2026). Pruritus is an itch or a sensation that makes a person want to scratch. "The aim of the study was to assess the frequency of IL-6 gene polymorphisms in CTCL patients, relationship between IL-6/STAT3 gene polymorphisms and IL-6 serum level and clinical values such as stage of the disease and pruritus." (PMID 32270320, 2021). "Persistent pruritus in AD leads to scratching, which in turn triggers STAT3 activation in astrocytes of the spinal dorsal horn." (PMID 36983094, 2023). "Behavioral evidence using NC/Nga mice suggested that STAT3-dependent spinal cord central sensitization occurs via amplification of GRP signalling under chronic itch conditions." (PMID 35095512, 2021). "The aim was to examine whether IL-6 cytokine and polymorphisms of IL-6 and STAT3 gene are associated with CTCL susceptibility, stage of disease and pruritus intensity." (PMID 32270320, 2021). "The presence of STAT3 rs4796793 GG genotype was strongly associated with lack of pruritus in CTCL (OR = 3.65, 95% CI 1.31–10.19, p = 0.014)." (PMID 32270320, 2021). "Interestingly, the GG genotype of rs4796793 STAT3 polymorphism was significantly more frequent in CTCL patients without pruritus (p = 0.01)." (PMID 32270320, 2021). "Clearly, some genes such as AKT1, ALB, BCL2, STAT3, JUN, ESR1, and TNF hold important positions within the network, indicating their strong relevance to the pathogenesis of pruritus and their potential as key targets for drug intervention." (PMID 39606625, 2024).
subarachnoid hemorrhage (7 papers, 2013 to 2024). A serious neurological disorder characterized by intracranial hemorrhage into the subarachnoid space. "PK2 has been shown to regulate the signaling mechanism between neurons and astrocytes by inducing the phosphorylation of Signal Transducer and Activator of Transcription 3 (STAT3) after subarachnoid hemorrhage, thus acting as an endogenous mechanism for self-repair." (PMID 34829877, 2021). "A previous study has found that increased expression of MFG-E8 can downregulate the phosphorylation of STAT3 and upregulate the expression of SOCS3, then promote M2 polarization and exert an anti-inflammatory effect after subarachnoid hemorrhage." (PMID 36717543, 2023). "In addition, the therapeutic effect of recombinant human erythropoietin (rhEPO) on the subsequent vasospasm after subarachnoid hemorrhage may relate to its inhibition of endothelial apoptosis in cerebral arteries, which may be mediated in part by the JAK2/STAT3 signaling pathway." (PMID 23483946, 2013).
tongue cancer (7 papers, 2019 to 2024). A malignant neoplasm affecting the tongue. "Many studies have reported that ezrin, ERK, STAT3, and AKT are associated with the development of tongue cancer cells and with the prognosis of patients with OTSCC." (PMID 32281236, 2020). "Ezrin, ERK, STAT3, and AKT are proteins that are overexpressed in various types of cancer, although their expressions in tongue cancer has received less focus." (PMID 32281236, 2020). "Therefore, we suggest that inhibited expression of genes involved in JAK2/STAT3 and MAPK signaling pathways might be related to the anticancer activities of DMU-214 and Gef in tongue cancer cells." (PMID 34201116, 2021). "The activation of the PI3 K/AKT and JAK2/STAT3 signaling pathways could promote the secretion of VEGF-C in cancer cells, suggesting that IER3 might induce the generation of VEGF-C in tongue cancer cells, but the specific molecular mechanism needs to be identified in further studies." (PMID 31832020, 2019).
ZIKV infection (7 papers, 2019 to 2026). "ZIKV infection also induces IL-6 secretion, most probably through the activation of the IL-6/STAT3 signaling pathway, which plays a key role in regulating inflammatory host immune responses during infections." (PMID 36483552, 2022). "Our observation of increased STAT3 phosphorylation upon ZIKV infection in the presence of TLR3 and the downregulation of STAT1 signaling is in agreement with the well-established interplay between these two transcription factors (recently reviewed in reference 69)." (PMID 33658344, 2021). "From our analysis, STAT3 may be a candidate for immune suppression by ZIKV infection, as several viruses reduced cellular STAT3 by promoting proteasomal degradation, and NS1 protein of dengue-2 virus directly interacted with human STAT3 protein." (PMID 32287277, 2020). "Additional studies focusing on each of these types of interferon I, II, and III, and their interplay with each other and with STAT3 in response to ZIKV infection, could help explain viral-induced host responses." (PMID 30984137, 2019). "Interestingly, immune escape by ZIKV infection could be caused by downregulation of prolactin signaling including IRS2, PIK3C3, JAK3, STAT3, and IRF1 as well as mitochondria dysfunction and oxidative phosphorylation in myeloid dendritic cells." (PMID 32287277, 2020). "Thus, to identify the mechanism by which NaAc, PBA, and NaB block the expression of these PRRs, cytokines, IFNs, and ISGs, we measured the activation of NFκB, MAPK (ERK1/2 and p38), STAT1, STAT2, and STAT3 signaling pathways in the presence and absence of these SCFAs following ZIKV infection." (PMID 41358724, 2026). "Indeed, ZIKV infection under conditions of antibody-mediated sequestration of IL-6, which was released from the cells into the culture supernatant, resulted in ∼3-fold-enhanced STAT1 phosphorylation (top blot), whereas STAT3 phosphorylation and SOCS3 expression were significantly reduced." (PMID 33658344, 2021). "Upon ZIKV infection of iPSC-derived astrocytes, we observed an almost 4-fold increase of pSTAT1 in cells treated with the TLR3 inhibitor (top blot, lane 4), whereas phosphorylation of STAT3 was decreased to the level of noninfected cells (compare lane 2 with lane 4)." (PMID 33658344, 2021).